HMGA1 (high mobility group AT-hook 1)
Diseases named in the same sentence as HMGA1 in open-access papers (continued):
Sharing a sentence is not in itself a finding about the gene and the disease.
Splenomegaly (2 papers, 2020 to 2025). Abnormal increased size of the spleen. "Surprisingly, the loss of just a single Hmga1 allele is sufficient to dampen the overproduction of red cells and platelets while preventing splenomegaly and progression to MF." (PMID 40076747, 2025). "Similar to JAK2-V617F mice with global, heterozygous Hmga1 deficiency, those with the loss of one Hmga1 allele restricted to HSCs have decreased erythrocytosis, thrombocytosis, splenomegaly, and fibrosis." (PMID 40076747, 2025). "They reported that complete loss of CDKN2A accelerated leukemogenesis in HMGA1 transgenic mice that showed marked splenomegaly and significantly decreased OS compared with HMGA1 transgenic/CDKN2A WT mice." (PMID 32503270, 2020).
Stroke (2 papers, 2022). Sudden impairment of blood flow to a part of the brain due to occlusion or rupture of an artery to the brain. "Therefore, understanding the roles of HMGA1 in oligodendrocyte lineage cells may help us to find a novel therapeutic approach for white matter-related CNS diseases, such as stroke or vascular dementia." (PMID 35216347, 2022).
uterine adenosarcoma (2 papers, 2013 to 2019). "HMGA1-induced expression targeted to mice uterine tissues is capable of driving the development of uterine adenosarcoma." (PMID 31096664, 2019).
uterine tumor (2 papers, 2019 to 2021). "The female Hmga1 transgenic mice also develop uterine tumors, in part, by inducing the gene encoding cyclo-oxygenase-2 (COX2)." (PMID 34572547, 2021). "Indeed, COX2 inhibitors (COXibs) repressed uterine tumor growth in the Hmga1 females and in xenografts of human uterine sarcomas in immunosuppressed mice." (PMID 34572547, 2021). "Additionally, high levels of HMGA1 mRNA were detected in high-grade, aggressive uterine tumors when compared with less aggressive uterine neoplasms." (PMID 31096664, 2019).
adenomyosis (1 paper, 2022). The growth of endometrial tissue inside the muscular wall of the uterine corpus. "We also did qPCR on the adenomyosis pain group and the non-pain group and discovered that several mRNAs associated with nerve growth and neuroinflammatory factors, NEFM, GATA2, HMGA1, and IGFBP6, were considerably more strongly expressed in the adenomyosis pain group than in the non-pain group." (PMID 36532077, 2022).
aortic aneurysm and dissection (1 paper, 2023). "HMGA1 has been found associated with the development of aortic aneurysm and dissection (AAD) via transcriptome-wide association study (TWAS) analysis and SERPINA1 has been identified as a reliable molecular marker for the early diagnosis of AD patients." (PMID 37877967, 2023).
Aortic dissection (1 paper, 2025). Aortic dissection refers to a tear in the intimal layer of the aorta causing a separation between the intima and the medial layers of the aorta. "In addition to PGK1 and HMGA1, several other lactylation-related genes identified in our analysis, such as GAPDH and ALDH1A1, may also contribute to the pathophysiological mechanisms of aortic dissection." (PMID 40596702, 2025).
bacterial sepsis (1 paper, 2021). "Thus, disrupting the HMGA1 pathway in MSCs provides an improved therapeutic response during bacterial sepsis." (PMID 33438259, 2021).
benign mesenchymal tumors (1 paper, 2020). "Similar translocations involving the chromosomal locus 6p21–23 corresponding to HMGA1 (HMGI-Y) have also been described in benign mesenchymal tumors, implicating the HMGI family of DNA-binding proteins." (PMID 32365712, 2020).
bile duct cancer (1 paper, 2023). "Furthermore, MYC can induce HMGA1 and TRIP13 transcription by bile duct cancer cells to enhance bile duct cancer cell migration, proliferation, invasion, dryness, and epithelial–mesenchymal transition (EMT)." (PMID 37504265, 2023).
Burkitt lymphoma (1 paper, 2025). A rare form of malignant mature B-cell non-Hodgkin lymphoma. "Indeed, prior studies showed that HMGA1 binds directly to the MYC promoter and induces cMYC in embryonic stem cells and iPSCs and, conversely, that HMGA1 is induced by cMYC in other settings (Burkitt lymphoma cells, transformed fibroblasts)." (PMID 40076747, 2025).
Cerebral ischemia (1 paper, 2019). Restriction of arterial blood supply to the brain associated with insufficient oxygenation to support the metabolic requirements of the tissue. "Previous works performed in a rat model of cerebral ischemia and in HUVEC cells showed an involvement of HMGA1 in modulating angiogenic proteins, such as Angiopoietin-1, a factor fundamental in maintaining the tumor vascularization." (PMID 31311575, 2019).
cervical tumour (1 paper, 2021). "Several other studies have reported miR-214 to suppress cervical tumour growth and metastasis through targeting and downregulating high mobility group AT-hook 1 (HMGA1), Plexin-B1, Bcl2l2, Ezh2, and forkhead box protein M1 (FOXM1)." (PMID 34943783, 2021).
chronic obstructive pulmonary disease (1 paper, 2018). A chronic and progressive lung disorder characterized by the loss of elasticity of the bronchial tree and the air sacs, destruction of the air sacs wall, thickening of the bronchial wall, and mucous accumulation in the bronchial tree. "BC collected from nonsmokers, healthy smokers, and smokers with chronic obstructive pulmonary disease (COPD) displayed a range of HMGA1 expression levels." (PMID 29581847, 2018).
colon adenocarcinoma (1 paper, 2012). "We found that HMGA1 is highly enriched in colon adenocarcinoma compared to normal tissue in 5/5 prior studies." (PMID 22276142, 2012).
cyst (1 paper, 2017). A sac-like closed membranous structure that may be empty or contain fluid or amorphous material. "To determine whether Hmga1 organoids remained in a cyst-like structure because they were comprised predominantly of undifferentiated Lgr5+ stem cells, we stained for the ISC marker, Lgr5-GFP+." (PMID 28452345, 2017). "Interestingly, the Hmga1 organoids generated from purified Lgr5+ ISCs adopt a cyst-like, spherical structure similar to the morphology observed in organoids treated with Wnt or engineered to overexpress Ascl2, a transcription factor important in maintaining stem cell identity in ISCs7." (PMID 28452345, 2017).
endotoxemia (1 paper, 2010). "We describe a novel targeted approach in modulating lung and liver inflammation in vivo during murine endotoxemia through decreasing binding of HMGA1 to a distinct AT-rich region of the P-selectin promoter." (PMID 20498830, 2010).
ependymoma (1 paper, 2025). A WHO grade II, slow growing tumor of children and young adults, usually located intraventricularly. "Importantly, in comparison to their controls, CR ependymoma cells demonstrated elevated expression of genes encoding High Mobility Group Protein AT-hook 1 (HMGA1), High Mobility Group Protein AT-hook 2 (HMGA2), cMYC, HOXB13, and HOXA10 proteins." (PMID 40940935, 2025).
esophageal tumors (1 paper, 2016). "Next, since ESCC and EAC represent the two main esophageal tumors histotypes, we investigated whether HMGA1 and HMGA2 expression could differ, according to the histological origin of the esophageal tumors." (PMID 27027341, 2016). "Together these results suggest that HMGA1 and HMGA2 proteins are differentially expressed, according to the esophageal tumor histopathological subtype." (PMID 27027341, 2016). "In this way, the antagonist HMGA1 and HMGA2 expression pattern observed in esophageal tumors (ESCC and EAC) could result from the activation of specific embrionary-like mechanisms during the distinct development of esophageal squamous cell and adenocarcinoma." (PMID 27027341, 2016).
Ewing sarcoma (1 paper, 2022). A small round cell tumor that lacks morphologic, immunohistochemical, and electron microscopic evidence of neuroectodermal differentiation. "qRT-PCR confirmed that CDS specimens exhibited significantly elevated expression of HMGA2, IGF2BP2, IGF2BP3, and IGF2, but not HMGA1, compared with Ewing sarcoma specimens." (PMID 34903601, 2022).
fatty liver (1 paper, 2025). "Furthermore, similar to ISG15, HMGA1 was also upregulated in clinic NAFLD samples compared with healthy liver tissues (GEO GSE130970), suggesting a potential association between HMGA1 and fatty liver." (PMID 40126377, 2025).
fibrosis (1 paper, 2021). the formation of excess fibrous connective tissue in an organ or tissue in a reparative or reactive process. "Our studies therefore delineate a novel HMGA1-mediated cardiac fibrosis mechanism and provide new insights into HMGA1-associated therapy in fibrosis disease." (PMID 34513822, 2021). "Collectively, our data demonstrated that HMGA1 plays a critical role in the development of cardiac fibrosis by regulating FOXO1 transcription." (PMID 34513822, 2021).
Flavivirus Infections (1 paper, 2023). Infections with viruses of the genus FLAVIVIRUS, family FLAVIVIRIDAE. "We next selected two of the most downregulated proteins in Flavivirus infections (previously identified in the SILAC experiment), HMGA1 and MRPS27, for validation by Western blot." (PMID 37515107, 2023).
glaucoma (1 paper, 2021). Increased pressure in the eyeball due to obstruction of the outflow of aqueous humor. "Analysis of the combined RNA-Seq and ChIP-Seq data showed that the transcription of several of the differentially expressed genes with roles in TM, IOP, and glaucoma, were directly regulated by GLIS1 and included MYOC, LTBP2, CHI3L1, HMGA1, CYP1B1, and LOXL1-4." (PMID 34385434, 2021).
herpesvirus infection (1 paper, 2025). "Moreover, pseudogenic lncRNAs can directly bind proteins to alter their activity or localization, including HMGA1‐p lncRNA interacts with the RNA‐stabilizing complex αCP1, destabilizing HMGA1 mRNA, RNA5SP141 binds RIG‐I during herpesvirus infection, triggering interferon production, and so on." (PMID 41473691, 2025).
hypothyroidism (1 paper, 2016). Abnormally low levels of thyroid hormone. "Furthermore, our data provide candidate molecular mechanisms (deregulated expression of Bcl2, Zfp36l2, Egr1 and Hmga1) for the pesticides-induced hypothyroidism." (PMID 27905518, 2016).
intestinal polyposis (1 paper, 2012). "We discovered that HMGA1 drives proliferative changes, aberrant crypt formation, and intestinal polyposis in transgenic mice." (PMID 22276142, 2012).
invasive breast carcinoma (1 paper, 2019). A carcinoma that infiltrates the breast parenchyma. "Upon identifying extracellular HMGA1 as a ligand of RAGE in TNBC cells, we determined that extracellular HMGA1 induced a decreased adhesive phenotype in invasive breast cancer cells." (PMID 31779212, 2019).
leiomyosarcoma (1 paper, 2024). An uncommon, aggressive malignant smooth muscle neoplasm, usually occurring in post-menopausal women. "In CP0024 leiomyosarcoma cells, HMGA1 silencing decreases the levels of phospho-S6, ranging from 17% (shHMGA1-281) to 34% (shHMGA1-446)." (PMID 38758230, 2024). "The AA leiomyosarcoma cell line showed the lowest expression of HMGA1 in our experimental conditions." (PMID 38758230, 2024). "HMGA1 silencing sensitized leiomyosarcoma cells for trabectedin treatment, reducing the spheroid area and increasing cell death." (PMID 38758230, 2024). "The effect of HMGA1 silencing on trabectedin activity and gene expression profiling was measured in leiomyosarcoma cells." (PMID 38758230, 2024). "First, we analyzed the effect of rapamycin pre-treatment (2 h before trabectedin treatment; rapamycin was washed out before trabectedin treatment) in the sensitivity of both leiomyosarcoma cell lines CP0024 (higher levels of HMGA1) and AA (lower levels of HMGA1)." (PMID 38758230, 2024). "The expression levels of HMGA1 were determined by mRNA and protein in a panel of 7 STS cell lines, to compare the expression of leiomyosarcoma cell lines with other STS histological subtypes." (PMID 38758230, 2024). "Of note, the prognostic value of HMGA1 intensity and expression for trabectedin PFS was significantly marked in leiomyosarcoma cases." (PMID 38758230, 2024). "In silico molecular dynamics studies should be performed to identify potential molecules that could bind and inhibit HMGA1, to be tested in preclinical models of STS, in particular leiomyosarcoma." (PMID 38758230, 2024). "Trabectedin drug resistance was tested in 3D spheroids and 2D monocultures after transducing the CP0024 cell line (leiomyosarcoma cell line with HMGA1 highest expression levels) with lentiviral particles containing shRNAs against HMGA1 (shHMGA1) and a control non-targeting shRNA (shControl)." (PMID 38758230, 2024).
lipodystrophy (1 paper, 2015). A congenital or acquired disorder characterized by abnormal loss or redistribution of the adipose tissue in the body. "Collectively, these results indicated that adipose-specific HMGA1 overexpression led to partial lipodystrophy in aP2-HMGA1 transgenic mice." (PMID 26411793, 2015).
malignant glioma (1 paper, 2022). A grade III or grade IV glioma arising from the central nervous system. "Previous studies showed that among malignant gliomas, HMGA1 is associated with Ki-67." (PMID 35629376, 2022).
metastatic melanoma (1 paper, 2017). A melanoma that has spread from its primary site to another anatomic site. "Genes encoding high-mobility group protein A1 (HMGA1), Kv Channel Interacting Protein 3 (KCNIP3) and Apolipoprotein B (APOB) shared promoter hypomethylation in all metastatic melanoma cell lines." (PMID 28030832, 2017).
myelodysplastic syndrome (1 paper, 2025). A clonal hematopoietic disorder characterized by dysplasia and ineffective hematopoiesis in one or more of the hematopoietic cell lines. "Translocations, duplications, and amplifications involving HMGA1 or HMGA2 have been reported in solid tumors, myeloid malignancies, such as myelodysplastic syndromes (MDS), and other hematologic malignancies, although such events are relatively infrequent." (PMID 40076747, 2025).
myeloid malignancies (1 paper, 2025). "Because high levels of GATA2 are linked to poor outcomes in myeloid malignancies and GATA2 was among the genes most differentially regulated by HMGA1, functional studies were performed to determine whether HMGA1 depends upon GATA2 and downstream networks for leukemic transformation in MPN models." (PMID 40076747, 2025).
myeloproliferative neoplasm (1 paper, 2023). A clonal hematopoietic stem cell disorder, characterized by proliferation in the bone marrow of one or more of the myeloid (i.e., granulocytic, erythroid, megakaryocytic, and mast cell) lineages. "Intriguingly, we recently found that HMGA1 causes bone marrow fibrosis during progression in mouse models of chronic myeloid malignancies (JAK2V617F myeloproliferative neoplasms), suggesting that fibrosis mediated by HMGA1 is relevant to diverse tumors." (PMID 36919699, 2023).
myocardial inflammation (1 paper, 2020). "Moreover, miR-26a acts on the inflammatory process by downregulating HMGA1 and MALT1, thus impacting the TNF-α/NF-κB inflammatory genes in human bronchial epithelial cells; in addition, the miR-26a/HMGA1 axis controls coronary microembolization-induced myocardial inflammation." (PMID 31979076, 2020).
nasopharyngeal carcinoma (1 paper, 2023). A carcinoma arising from the nasopharyngeal epithelium. "Among these mRNAs, only HMGA1 was found to be related to the overall survival and disease-free survival of nasopharyngeal carcinoma patients which will be further validated in a larger population." (PMID 37710236, 2023). "Among the nodes in the PPI network based on the mRNAs in the ceRNA network, HMGA1 was assessed in relation to the overall and disease-free survival of nasopharyngeal carcinoma." (PMID 37710236, 2023). "As a result, only HMGA1 was found to be related to the prognosis of nasopharyngeal carcinoma." (PMID 37710236, 2023). "Nevertheless, there is no research report on the role of HMGA1 in nasopharyngeal carcinoma." (PMID 37710236, 2023).
Osteopenia (1 paper, 2023). Osteopenia is a term to define bone density that is not normal but also not as low as osteoporosis. "Hmga1-knockout mice have decreased embryonic viability, whereas those that survive development are slightly small but appear grossly normal up to 30 weeks of age when they develop signs of premature aging (graying, osteopenia, decreased gait velocity)." (PMID 36919699, 2023).
pleural mesothelioma (1 paper, 2022). A neoplasm that arises from the mesothelial cells of the pleura. "By mediating miR-1294/HMGA1, circPLK1 promoted the abilities of malignant pleural mesothelioma to proliferate, migrate, invade, and keep stemness." (PMID 36059626, 2022).
reproductive system cancer (1 paper, 2022). "Indeed, tissue-specific upstream and downstream regulation of HMGA1 was described in head and neck, thoracic, reproductive system cancer, and other abdominal tumors." (PMID 35805937, 2022).
salivary gland tumor (1 paper, 2023). "One KPC/Hmga1 heterozygous mouse developed a large salivary gland tumor at 7.4 weeks of age; the pancreas showed only rare foci of acinar ductal metaplasia." (PMID 36919699, 2023).
Small intestinal tumors (1 paper, 2025). "Small intestinal tumors also decrease modestly in this model, but only with homozygous loss of Hmga1." (PMID 39895630, 2025).
soft tissue sarcoma (1 paper, 2024). A malignant neoplasm arising from muscle tissue, adipose tissue, blood vessels, fibrous tissue, or other supportive tissues excluding the bones. "Here, we reported the prognostic/predictive value of HMGA1 for trabectedin in advanced soft-tissue sarcoma (STS) and the effect of inhibiting HMGA1 or the mTOR downstream pathway in trabectedin activity." (PMID 38758230, 2024).
Ta (1 paper, 2005). "Among the mostly changed genes between normal bladder and Ta tumours, we found genes related to the cytoskeleton (keratin 7 and syndecan 1), and transcription (high mobility group AT-hook 1)." (PMID 16265353, 2005).
testicular cancer (1 paper, 2010). A primary or metastatic malignant neoplasm that affects the testis. "Thus, different expression profiles of HMGA1/2 protein could be utilized as a tumor marker in testicular cancer cases with a problematic histological differential diagnosis." (PMID 20535291, 2010). "In addition to HMGA1/2 and OCT3/4, SOX proteins have also been reported as potential “new” markers for testicular cancer." (PMID 20535291, 2010).
thyroid (1 paper, 2019). "Indeed, ~50% of HIPK2/HMGA1 DKO mice display perinatal lethality associated to respiratory distress and thyroid abnormalities." (PMID 31582725, 2019).
uterine sarcomas (1 paper, 2021). "HMGA1 and COX2 are also up-regulated and co-expressed in human uterine sarcomas (leiomyosarcomas) in addition to pancreatic tumors." (PMID 34572547, 2021).